RN7SL203P (RNA, 7SL, cytoplasmic 203, pseudogene)
Gene: Miscellaneous RNA gene on chromosome 8 (70,480,192 to 70,480,487, reverse strand). Ensembl gene ENSG00000275128.
Homologues: Orthologues: chimpanzee Metazoa_SRP (99% identical), macaque Metazoa_SRP (94% identical). Paralogues in human: RN7SL1 (82% identical), RN7SL2 (82% identical), RN7SL45P (81% identical), RN7SL3 (81% identical), RN7SL220P (80% identical), RN7SL566P (80% identical), RN7SL575P (80% identical), RN7SL597P (80% identical), RN7SL11P (79% identical), RN7SL322P (79% identical), RN7SL431P (79% identical), RN7SL321P (79% identical), and 702 more.